RNU6-105P (RNA, U6 small nuclear 105, pseudogene)
Gene: Small nuclear RNA gene on chromosome 2 (71,379,755 to 71,379,858, reverse strand). Ensembl gene ENSG00000200779.
Homologues: Orthologues: chimpanzee U6 (98% identical), macaque U6 (91% identical), dog U6 (78% identical). Paralogues in human: RNU6-116P (89% identical), RNU6-47P (89% identical), RNU6-1060P (88% identical), RNU6-15P (88% identical), RNU6-33P (88% identical), RNU6-1 (88% identical), RNU6-11P (88% identical), RNU6-2 (88% identical), RNU6-37P (88% identical), RNU6-3P (88% identical), RNU6-4P (88% identical), RNU6-5P (88% identical), and 1286 more.